TRAF3IP3 (TRAF3 interacting protein 3)
Diseases named in the same sentence as TRAF3IP3 in open-access papers (continued):
Sharing a sentence is not in itself a finding about the gene and the disease.
lung adenocarcinoma (3 papers, 2022 to 2025). A carcinoma that arises from the lung and is characterized by the presence of malignant glandular epithelial cells. "Consistently, the expression level of TRAF3IP3 was dramatically downregulated in patients with primary lung adenocarcinoma." (PMID 40068093, 2025). "A recent study showed that TRAF3IP3-mediated ER stress induced protective autophagy by activating the PERK–ATF4–CHOP pathway to regulate the growth of lung adenocarcinoma cells." (PMID 41408408, 2025). "In the present study, we report that TRAF3IP3 can trigger sustained and potent ER stress in lung adenocarcinoma cells, leading to the decline of cell growth and enhancement of cell apoptosis." (PMID 40068093, 2025). "Among the 33 different types of human cancers, TRAF3IP3 mRNA expression was found to be down‐regulated only in lung adenocarcinoma (LUAD) and lung squamous carcinoma (LUSC)." (PMID 40068093, 2025). "To investigate the functional significance of TRAF3IP3 in the progression of human lung adenocarcinoma, we conducted stable TRAF3IP3‐overexpression A549 and PC9 cell lines and TRAF3IP3‐knockdown PC9 and H1299 cell lines through lentiviral transfections, respectively." (PMID 40068093, 2025). "Upregulation of TRAF3IP3 correlates with Lung adenocarcinoma progression." (PMID 40068093, 2025). "However, the specific effects and molecular mechanisms of TRAF3IP3 on the progression of lung adenocarcinoma (LUAD) remains poorly understood." (PMID 40068093, 2025). "TRAF3IP3 can be used as a prognostic signature for OS in patients with lung adenocarcinoma." (PMID 36185204, 2022).
COVID-19 (2 papers, 2022). A disease caused by infection with severe acute respiratory syndrome coronavirus 2. "Among them, S100A9, AHNAK, and CX3CR1 have been reported as potential COVID-19 biomarkers previously, and the others (TRAF3IP3 and LFNG) are closely associated with the immune and virus-related signaling pathways." (PMID 35885892, 2022). "Several genomic and methylation studies on COVID-19 have found that TRAF3IP3 can serve as a potential epigenetic biomarker for COVID-19 and is a key mutated region in severe patients, compared with non-severe COVID-19 patients." (PMID 36551164, 2022). "We speculate that TRAF3IP3 and LFNG methylation variations may serve as potential epigenetic biomarkers for COVID-19, and that they play a role in important biological processes like the immune response and antiviral activity." (PMID 35885892, 2022). "Notably, we identified two genes (TRAF3IP3 and LFNG) that have not been reported to be associated with COVID-19, which may be potential COVID-19 biomarkers or involved in the immune response to COVID-19." (PMID 35885892, 2022).
lung carcinoma (2 papers, 2020 to 2025). "Under conditions of ER stress, TRAF3IP3 overexpression was observed to result in increased ER protein levels in lung cancer cells, with opposite results in TRAF3IP3 knockdown lung cancer cells." (PMID 40068093, 2025). "Schematic diagram of the working model of TRAF3IP3 in the coordination of ER stress and autophagy related apoptosis in lung cancer cells." (PMID 40068093, 2025). "And there was a greater elevation in ER proteins following thapsigargin treatment in TRAF3IP3‐overexpressed lung cancer cells." (PMID 40068093, 2025). "Through flow cytometry analyses, either PERK or ATF4 knockdown could significantly rescue apoptosis triggered by TRAF3IP3 overexpression in lung cancer cells." (PMID 40068093, 2025). "Although previous studies have shown that STRN3 is essential for ER stress, it is unclear whether it is involved in cellular physiological processes like TRAF3IP3 in lung cancer, such as regulating apoptosis and prolonged ER stress." (PMID 40068093, 2025). "Together, our data implies that the overexpression of TRAF3IP3 triggers ER stress and UPR activation in lung cancer cells." (PMID 40068093, 2025). "The intense interaction between endogenous TRAF3IP3 and STRN3 in lung cancer cells was validated by co‐immunoprecipitation (Co‐IP) using A549, PC9, and H1299 cell lysates." (PMID 40068093, 2025). "A subset of the 11 gene signature has recently been reported in the context of lung cancer, either as an oncogenic driver (e.g. CD79B) or a prognostic marker (e.g. TRAF3IP3, SKAP2, and SS18L2)." (PMID 33287695, 2020).
bipolar affective disorder (1 paper, 2022). "Until now, only the rs2492367 polymorphism in DISC1 has been shown to be associated with the bipolar affective disorder; there were no reports about the other SNPs of PTPRB, TRAF3IP3, and DISC1 genes that can affect protein function and disease." (PMID 36397361, 2022).
cleft lip (1 paper, 2019). Congenital defect in the upper lip where the maxillary prominence fails to merge with the merged medial nasal prominences. "We detected one de novo deletion in the gene TRAF3IP3 on chromosome 1q32 in a Caucasian proband with a cleft lip." (PMID 30084993, 2019).
Lung squamous cell carcinoma (1 paper, 2025). "This study reveals TRAF3IP3 is upregulated in several tumor tissues but exclusively decreased in LUAD and Lung squamous cell carcinoma (LUSC) tissues, consequential in a favorable overall survival (OS) in LUAD rather than LUSC." (PMID 40068093, 2025).
rhabdomyosarcoma (1 paper, 2022). A rare aggressive malignant mesenchymal neoplasm arising from skeletal muscle. "Furthermore, TRAF3IP3 showed antiviral activity in Jurkat and rhabdomyosarcoma (RD) cells, making this the first report of TRAF3IP3 inhibition of an enterovirus." (PMID 35814660, 2022). "In Jurkat and rhabdomyosarcoma (RD) cells, TRAF3IP3 inhibited EV71 replication, and 3Cpro cleavage partially resisted TRAF3IP3-induced inhibition." (PMID 35814660, 2022).
thyroid autoimmune (1 paper, 2021). "Therefore, further studies are necessary to figure out whether the variations of PTPRB, PIK3R3 and TRAF3IP3 are involved in the dysfunction of thyroid autoimmune." (PMID 33568133, 2021).
tumor (12 papers, 2018 to 2025). "Primarily involved in regulating lymphocyte development, TRAF3IP3 has been linked to tumor progression." (PMID 39677949, 2024). "Tumor necrosis factor receptor-associated factor 3 (TRAF3)-interacting protein 3 (TRAF3IP3) expressed in various tumor cell." (PMID 39677949, 2024). "In conclusion, SLAMF1 and TRAF3IP3 were identified with higher expression in tumor tissues and associated with tumor recurrence." (PMID 36281288, 2022). "Four genes (CENPH, MYLIP, PITX3, and TRAF3IP3) were eventually identified; these were associated with tumor-infiltrating immune cells, the proliferation of tumor cells, and cell adhesion." (PMID 34631307, 2021). "Since ER stress has been shown to be strongly associated with tumor cell proliferation and apoptosis by previous studies, we assume that TRAF3IP3 may play a role in regulating ER stress in LUAD cells." (PMID 40068093, 2025). "In conclusion, TRAF3IP3 could influence tumor-associated macrophages and there was a more favorable immune environment in the TRAF3IP3 high group." (PMID 39166607, 2024). "The comparison graph demonstrated that the tumor size of A549‐vector cells was significantly less than that of TRAF3IP3‐overexpression cells." (PMID 40068093, 2025). "Through bioinformatics analysis using the biological database (TCGA, UALCAN), we found that TRAF3IP3 was highly expressed in several tumor tissues." (PMID 40068093, 2025). "This signature, comprising CCL19, ICOSLG, IL11, PTGES, TNFAIP3, and TRAF3IP3, has been demonstrated to predict survival outcomes across a range of cancers and to correlate with tumor progression at the level of multi‐omics." (PMID 40714831, 2025). "Subsequently, we detected the expression of TRAF3IP3 in tumor tissues versus matched normal tissues by conducting immunohistochemistry (IHC) analysis on 126 LUAD patients at our single center." (PMID 40068093, 2025). "Our findings align with our initial estimations, showing that high TRAF3IP3 expression is strongly correlated with favorable prognosis in tumor patients undergoing immunotherapy." (PMID 39677949, 2024). "The baseline datasheet showed that TRAF3IP3 was significantly correlated with the tumor status, weight and the fibrosis Ishak score." (PMID 39677949, 2024). "Based on the results of pan-cancer analysis, we found that GLRX2, NMT1, PPP2R2B and TRAF3IP3 exhibited a dysregulated level in many types of tumors, highlighting their potential roles in tumor progression." (PMID 38409085, 2024). "In this study, we observed that TRAF3IP3 expression was distinctly decreased in BC specimens suggesting it as a tumor promotor in BC." (PMID 38654047, 2024). "The AOD value of TRAF3IP3 immunohistochemical staining in adjacent normal liver tissues was higher compared to tumor tissues, indicating lower TRAF3IP3 expression in tumor tissues than in adjacent normal liver tissues." (PMID 39677949, 2024). "Results showed that TRAF3IP3 mRNA expression was lower in HCC tumor tissues compared to normal tissues." (PMID 39677949, 2024). "The level of TRAF3IP3 expression showed a significant correlation with the presence of tumor-infiltrating CD8+ T cells." (PMID 39677949, 2024). "Based on data from the TCGA database, we utilized the ESTIMATE algorithm to calculate the stroma score, immune score, and estimate score of tumor samples and assessed the correlation between TRAF3IP3 expression levels and those scores." (PMID 39677949, 2024). "Immunotherapy is increasingly demonstrating its advantages in tumor treatment, prompting us to analyze the relationship between TRAF3IP3 and immune factors, such as immune cells." (PMID 39677949, 2024). "The function of TRAF3IP3 in tumor inhibition and its relationship with macrophages in clinical tissue samples were in accordance with bioinformatics analysis results." (PMID 39166607, 2024). "Our findings provide additional insight into using TRAF3IP3 as a target to control tumor growth and development." (PMID 36185204, 2022).
tumor (continued). "Recent studies show that TRAF3IP3 positively correlated with pathological tumor and lymph node stages." (PMID 36185204, 2022). "We explained that SLAMF1 and TRAF3IP3 were low-expressed in HBV-associated HCC tissues and were correlated with tumor recurrence." (PMID 36281288, 2022). "We identified that TRAF3IP3 was positively correlated with all six types of immune infiltrating lymphocytes, thus suggesting that this gene is closely related to tumor immune infiltration." (PMID 34631307, 2021). "KIRC patients with low or medium expression of TRAF3IP3 and low tumor grade possibly had a good overall survival." (PMID 32754603, 2020). "There were significantly comparable methylation levels of PPP2R1A and TRAF3IP3 between normal and tumor tissue." (PMID 32754603, 2020). "The methylation level of TRAF3IP3 gradually reduced with increased tumor grade and lymph node metastasis status." (PMID 32754603, 2020). "The CCK8 proliferation and colony formation assay revealed that TRAF3IP3 could markedly suppress tumor cell growth and colony frequency and size in A549 and PC9 cell lines, respectively." (PMID 40068093, 2025). "Moreover, in six pairs of samples, TRAF3IP3 protein levels in tumor tissues were found to be lower than those in adjacent non‐cancerous tissues." (PMID 40068093, 2025). "Proteomic analysis suggests that the ER stress pathway may be involved in TRAF3IP3‐mediated tumor suppression and autophagy." (PMID 40068093, 2025). "Furthermore, TRAF3IP3 expression correlated with the Ishak score and tumor status, indicating its potential as an independent prognostic biomarker for patients with HCC." (PMID 39677949, 2024). "We proposed that the expression of SNORA5A may affect the tumor microenvironment through TRAF3IP3, and TRAF3IP3 was chosen for further study." (PMID 39166607, 2024). "Recent studies have confirmed the key role of TRAF3IP3 in tumor progression." (PMID 39166607, 2024). "Additionally, we explored the relationship between TRAF3IP3 and tumor microenvironment (TME) scores, immune cell infiltration, and immune checkpoint." (PMID 39677949, 2024). "In vivo, remarkable promotion of tumor growth was observed following TRAF3IP3 overexpression." (PMID 36185204, 2022). "TRAF3IP3 overexpression also promoted in vivo tumor growth in a nude mouse xenograft model." (PMID 36185204, 2022). "The results showed that SLAMF1 and TRAF3IP3 were inversely associated with tumor recurrence, regardless of gender, age, tumor stage (T), lymph node stage (N), and metastasis stage (M)." (PMID 36281288, 2022). "We speculate that the effect of TRAF3IP3 may be related to its positive regulation of tumor-infiltrating immune cells." (PMID 34631307, 2021). "Furthermore, our research showed that the extent of tumor-infiltrating CD4+ T cells was positively correlated with the expression of TRAF3IP3 (correlation coefficients of 0.55 and 0.54 for the training and validation sets, respectively)." (PMID 34631307, 2021). "Furthermore, we revealed the connection between TRAF3IP3 and tumor immunotherapy response." (PMID 39677949, 2024). "In contrast, tumors generated from TRAF3IP3‐knockdown PC9 cells showed a greater size than those from control cells, as well as the tumor weight." (PMID 40068093, 2025). "Through single‐cell analysis of published and in‐house datasets, TRAF3IP3 exhibited selective enrichment in NPC‐like and MES‐like tumor cells, and showed a dual functionality in mediating T‐Cell Exhaustion." (PMID 40714831, 2025). "Patients with higher TNM stages (II‐III) showed lower TRAF3IP3 expression than patients with TNM stage I, as well as tumor grade, according to the TCGA dataset analysis." (PMID 40068093, 2025). "To summarize, the present study first demonstrated that TRAF3IP3 localizes to the ER in LUAD cells and inhibits tumor cell proliferation in vitro and in vivo." (PMID 40068093, 2025).
tumor (continued). "To further investigate the influence of TRAF3IP3 on HCC development, we initially examined its role in the TME, which is composed mainly of tumor cells, immune cells, and stromal cells.." (PMID 39677949, 2024). "The results showed that TRAF3IP3, WIPI1, ARHGAP11A, and RHOQ were significantly differentially expressed in normal and tumor tissue, displaying good classification performance." (PMID 36185204, 2022). "We also showed that tumor-infiltrating B cells were also positively correlated with TRAF3IP3 expression; B cells have also been reported to be actively proliferating in tumors, This suggests that the regulatory system for this gene in B cells may also be present in the tumor microenvironment." (PMID 34631307, 2021). "The promoter methylation of TRAF3IP3 was observed higher in normal tissue than KIRC tissue, and related with tumor grade and nodal metastasis status." (PMID 32754603, 2020). "Additionally, we observed a strong correlation between TRAF3IP3 expression and chemokines, as well as chemokine receptors in HCC, indicating a potential role of TRAF3IP3 in the immune response of tumor cells to immunotherapy." (PMID 39677949, 2024). "Notably, the ERK signaling pathway inhibitor U0126 drastically attenuated the effects of TRAF3IP3 on p-ERK and markedly blocked its tumor-promoting activity." (PMID 36185204, 2022). "Except tumor grade, the correlation between the expression of TRAF3IP3 and clinicopathological features showed no significance performed by UALCAN (Data not show)." (PMID 32754603, 2020). "Hence, there was a negative association between TRAF3IP3 expression and TNM stage, tumor grade, and T stage in both mRNA and protein levels." (PMID 40068093, 2025). "Furthermore, compared with adjacent nontumor tissues, TRAF3IP3 and SLAMF1 were highly expressed in tumor tissues and were linked to tumor recurrences." (PMID 36281288, 2022).
cancer (9 papers, 2018 to 2025). A tumor composed of atypical neoplastic, often pleomorphic cells that invade other tissues. "TNF receptor‐associated factor 3 interacting protein 3 (TRAF3IP3/T3JAM) exhibits dual roles in cancer progression." (PMID 40068093, 2025). "At the transcriptomic level, we found that CCL19 and TRAF3IP3 were protective factors in pan‐cancer, whereas IL11, PTGES, and TNFAIP3 were risk factors." (PMID 40714831, 2025). "Briefly, these findings initially confirmed the anti‐cancer impact of TRAF3IP3 on the development and growth of LUAD cells, both in vivo and in vitro." (PMID 40068093, 2025). "Thus, TRAF3IP3 may be associated with cancer progression-related pathways." (PMID 36185204, 2022). "To investigate the functional importance of TRAF3IP3 in various human cancers, we initially examined the expression levels of TRAF3IP3 across different types of cancer in humans via the Cancer Genome Atlas (TCGA) RNA‐seq data accessed through GEPIA (Gene Expression Profiling Interactive Analysis)." (PMID 40068093, 2025). "The significant correlation between TRAF3IP3 and multiple immune checkpoints piqued our interest, particularly in the context of the promising clinical application of immune checkpoint therapy in cancer treatment." (PMID 39677949, 2024). "These genes include SERTAD4, IRF6, TRAF3IP3, and UTP25, which are involved in embryo development, cancer, innate immune response, and epigenetic processes." (PMID 40007031, 2025). "On the basis of GSE136247 and GSE121248, the expression of each gene in cancer tissue and normal tissue was verified, and two key genes were finally obtained, namely, SLAMF1 and TRAF3IP3." (PMID 36281288, 2022). "Herein, in LUAD cancer cells, A549 and PC9 TRAF3IP3‐overexpression cell lines displayed decreased cancer proliferation and increased apoptosis without cytotoxic effects on cancer cell migration and invasion ability." (PMID 40068093, 2025). "Subsequently, immunohistochemistry was performed to assess the expression levels of TRAF3IP3 in both cancer and non-cancer tissues of patients with HCC." (PMID 39677949, 2024). "Furthermore, we analyzed the disease gene network (DGN) and the cancer gene network (CGN), wherein the DEGs between the TRAF3IP3 high- and low-expression groups were significantly enriched." (PMID 36185204, 2022). "The Cancer Genome Atlas (TCGA), Gene Expression Omnibus (GEO), Genotype-Tissue Expression (GTEx), KM-Plotter, University of Alabama at Birmingham Cancer data analysis Portal (UALCAN), and Xiantao Academic Online Website were utilized for the systematic analysis of TRAF3IP3." (PMID 39677949, 2024). "Immunohistochemistry on 20 paired HCC samples validated these findings, showing strong immunohistochemical staining of TRAF3IP3 in the cytoplasm of adjacent noncancerous tissues, while weak staining was observed in HCC cancer tissues." (PMID 39677949, 2024).
infection (3 papers, 2020 to 2023). The state of being infected such as from the introduction of a foreign agent such as serum, vaccine, antigenic substance or organism. "At 12 h post-infection, Western blotting of cell lysates showed that wild-type TRAF3IP3 inhibited the replication of EV71, while G88A had a stronger inhibitory effect." (PMID 35814660, 2022). "RD cells were transfected to overexpress TRAF3IP3, Δ30–37, or Δ407–416, followed by infection with EV71 at 1 MOI for 12 h." (PMID 35814660, 2022). "Third, consistent with the research about TRAF3IP3, we constructed the in vivo infection model using mice specifically lack VANGL2 in myeloid cells to verify the harmful role of VANGL2 in vivo, especially in macrophages, which differs from the study about USP38 that used USP38-KO mice." (PMID 37352355, 2023). "Reporter assay represents an artificial system, thus we next showed that overexpression of TRAF3IP3 also significantly inhibited IFN-β protein secretion induced by cytosolic poly(I:C), poly(dA:dT), 5′ppp-dsRNA stimulation or VSV infection." (PMID 32366851, 2020).